GNG4 (G protein subunit gamma 4)
Description:
Guanine nucleotide-binding proteins (G proteins) are involved as a modulator or transducer in various transmembrane signaling systems. The beta and gamma chains are required for the GTPase activity, for replacement of GDP by GTP, and for G protein-effector interaction.
Synonyms: HG3C
Tractability: Antibody: UniProt places it where antibodies can reach, with high confidence; its Gene Ontology location is reachable by antibodies, with high confidence. PROTAC: ubiquitination databases record sites on it; its protein half-life has been measured.
Gene: Protein-coding gene on chromosome 1 (235,547,685 to 235,650,754, reverse strand). Ensembl gene ENSG00000168243.
Subcellular location: Cell membrane
Pathways (Reactome):
Signal Transduction: Ca2+ pathway; Extra-nuclear estrogen signaling; G alpha (12/13) signalling events; G alpha (i) signalling events; G alpha (q) signalling events; G alpha (s) signalling events; G alpha (z) signalling events; G beta:gamma signalling through BTK; G beta:gamma signalling through CDC42; G beta:gamma signalling through PI3Kgamma; G beta:gamma signalling through PLC beta; G-protein activation; GPER1 signaling; Glucagon-type ligand receptors
Hemostasis: ADP signalling through P2Y purinoceptor 1; ADP signalling through P2Y purinoceptor 12; Prostacyclin signalling through prostacyclin receptor; Thrombin signalling through proteinase activated receptors (PARs); Thromboxane signalling through TP receptor
Metabolism: Adrenaline,noradrenaline inhibits insulin secretion; Glucagon signaling in metabolic regulation; Glucagon-like Peptide-1 (GLP1) regulates insulin secretion
Neuronal System: Activation of G protein gated Potassium channels; Inhibition of voltage gated Ca2+ channels via Gbeta/gamma subunits; Presynaptic function of Kainate receptors
Cellular responses to stimuli: High laminar flow shear stress activates signaling by PIEZO1 and PECAM1:CDH5:KDR in endothelial cells
Disease: ADORA2B mediated anti-inflammatory cytokines production
Metabolism of proteins: Cooperation of PDCL (PhLP1) and TRiC/CCT in G-protein beta folding
Transport of small molecules: Vasopressin regulates renal water homeostasis via Aquaporins
Gene Ontology:
Molecular function: protein binding; G-protein beta-subunit binding
Biological process: negative regulation of cell growth; G protein-coupled receptor signaling pathway; regulation of G protein-coupled receptor signaling pathway
Cellular component: extracellular exosome; heterotrimeric G-protein complex; plasma membrane; synapse
Genetic constraint (gnomAD): Loss-of-function variants: 4 observed, 3.3 expected, observed/expected ratio (o/e) 1.21, 90% interval 0.56 to 1.9. That is too few expected variants to judge how well the gene tolerates losing a copy. Missense variants: 59 observed, 59.63 expected, observed/expected ratio (o/e) 0.99, 90% interval 0.8 to 1.23. Synonymous variants: 18 observed, 19.4 expected, observed/expected ratio (o/e) 0.93, 90% interval 0.64 to 1.38.
Homologues: Orthologues: chimpanzee GNG4 (100% identical), guinea pig GNG4 (100% identical), dog GNG4 (99% identical), mouse Gng4 (99% identical), pig GNG4 (99% identical), rat Gng4 (99% identical), macaque GNG4 (95% identical), tropical clawed frog gng4 (91% identical), zebrafish GNG4 (88% identical). Paralogues in human: GNG2 (72% identical), GNG3 (69% identical), GNG7 (57% identical), GNG8 (56% identical), GNG12 (53% identical), GNG10 (43% identical), GNG5 (43% identical), GNG5B (41% identical), GNGT1 (32% identical), GNG11 (31% identical), GNGT2 (31% identical).
Diseases named in the same sentence as GNG4 in open-access papers:
GNG4 is named in the same sentence as 39 diseases in open-access papers, as found by Europe PMC text mining. Sharing a sentence is not in itself a finding about the gene and the disease. The quoted sentences say what the papers report.
breast cancer (7 papers, 2019 to 2024). A primary or metastatic malignant neoplasm involving the breast. "GNG4 is hypermethylated in breast cancer; however, when comparing all molecular subtypes, the HER2 subtype shows the highest expression levels for this gene." (PMID 36338974, 2022). "Although GNG4 has been reported to be hypermethylated and down-regulated in bladder cancer, breast cancer, and glioblastoma, other studies have shown that GNG4 expression was significantly up-regulated in lung carcinoma, and colorectal cancer." (PMID 36503584, 2022). "In contrast, CXCL9 has been shown to predict good outcomes for cancer patients; HCAR3 and GNG4 exhibit suppressor effects on the process of tumorigenesis in mammary cancer and in GBM." (PMID 31469863, 2019). "As expected, methylation levels of ADCY4, CPXM1, DNM3, GNG4, MAST1, PRDM14, and ZNF177 were found to be increased in breast cancer, and all with p values lower than 0.001." (PMID 33499882, 2021). "Recent research have indicated that GNG4 is up-regulated in several cancers including liver non-small-cell lung, bladder, and breast cancers, which is related to the poor prognosis." (PMID 39552710, 2024).
colorectal cancer (7 papers, 2021 to 2023). A primary or metastatic malignant neoplasm that affects the colon or rectum. "GNG4 was also demonstrated to be the key element of the colorectal carcinoma (CRC) tumor mutation burden (TMB), which is essential information in the ICB therapy of CRC." (PMID 35456499, 2022). "In conclusion, GNG4 may be an oncogene for colorectal cancer and may become a suitable new diagnostic marker and therapeutic target for colorectal cancer treatment." (PMID 34691179, 2021). "G protein subunit gamma 4 (GNG4) has been shown to participate in tumour progression and the tumour mutation burden (TMB) in colorectal cancer." (PMID 37448185, 2023). "As a tumor suppressor gene, abnormal expression of GNG4 was reported in multiple cancers containing colorectal cancer, bladder cancer, and glioblastoma." (PMID 35620462, 2022). "It has been reported that GNG4 is up-regulated in colorectal carcinoma and liver metastases from colorectal carcinoma tissues, which is related to the OS and tumor-free survival of colorectal carcinoma patients." (PMID 36397165, 2022). "The results showed that the mRNA and protein expression levels of GNG4 in patients with colorectal cancer were significantly higher than in normal people." (PMID 34691179, 2021). "Another similar study found that GNG4 was elevated in colorectal cancer patients who were sensitive to cetuximab treatment." (PMID 34691179, 2021). "Sequencing data, immunohistochemistry, and Kaplan–Meier analysis were used to explore GNG4 clinical significance in colorectal cancer." (PMID 34691179, 2021). "GNG4 is high-expressed and closely related to poor prognosis in colorectal cancer." (PMID 36299585, 2022). "In summary, GNG4 may be of importance in the therapy of the colorectal cancer; therefore, targeting GNG4 may have certain clinical value in the treatment of colorectal cancer." (PMID 34691179, 2021). "However, studies have shown that the expression of GNG4 is significantly upregulated in colorectal cancer, although its role is unclear." (PMID 34691179, 2021). "In this study, we reported significantly increased expression of GNG4 in colorectal cancer." (PMID 34691179, 2021). "This shows that GNG4 may play a role in promoting tumor development in colorectal cancer, therefore representing a potential therapeutic target." (PMID 34691179, 2021). "Thus, a deeper understanding of the molecular mechanism of GNG4 in the development of colorectal cancer may lead to new therapeutic strategies." (PMID 34691179, 2021). "Moreover, we verified the expression of GNG4 in colorectal cancer with RT-PCR." (PMID 34691179, 2021).
glioblastoma (7 papers, 2016 to 2024). The most malignant astrocytic tumor (WHO grade IV). "As indicated, the mechanism underlying the GNG4-silencing driven promotion of glioblastoma may be the inhibition of SDF1α/CXCR4 signaling." (PMID 34016944, 2021). "The focus of studies on the nervous system indicates that GNG4 is related to glioblastoma and cognitive decline." (PMID 39552710, 2024). "GNG4 is reported to be hypermethylated in bladder cancer and glioblastoma, and its expression significantly decreased." (PMID 34691179, 2021). "Hyper methylation of GNG4 is reported in glioblastoma and bladder cancer." (PMID 39552710, 2024). "However, other studies have found that GNG4 is hypermethylated in glioblastoma and bladder cancers, and its expression was significantly downregulated." (PMID 34691179, 2021). "Thus, this study identifies GNG4 as an inhibitor of SDF1α/CXCR4-dependent signaling and emphasizes the significance of epigenetic inactivation of GNG4 in glioblastoma, especially in mesenchymal subtype." (PMID 27382437, 2016). "Collectively from all these results, we conclude that epigenetic silencing of GNG4 in glioblastoma, specifically the mesenchymal subtype, is essential because its expression would inhibit GBM cell migration mainly through inhibition of ERK pathway downstream to SDF1α/CXCR4-dependent signaling." (PMID 27382437, 2016).
bladder cancer (6 papers, 2021 to 2024). "In this study, we integrated the public bulk and single-cell RNA sequencing data to comprehensively investigate the GNG4 expression in tumor microenvironment and its relationship with immunotherapy response in bladder cancer." (PMID 35456499, 2022). "Also, GNG4 can be introduced as a potential biomarker to predict immunotherapy response in bladder cancer." (PMID 39552710, 2024). "Notably, hypermethylated GNG4 was found in bladder cancer and glioblastoma." (PMID 37448185, 2023). "However, the potential role of GNG4 in bladder cancer (BLCA) is unknown." (PMID 35456499, 2022). "Interestingly, GNG4 expression is negatively correlated with overall survival and progression-free survival in bladder cancer patients who did not receive immunotherapy, which might be because GNG4 plays a role in developing chemo-resistance in bladder cancer." (PMID 35456499, 2022).
rectal cancer (6 papers, 2015 to 2024). A primary or metastatic malignant neoplasm that affects the rectum. "Some studies have also suggested GNG4 as an unfavorable marker for rectal cancer and gallbladder cancer." (PMID 39552710, 2024). "GEPIA results showed that the expression of GNG4 in colon cancer was obviously higher than that in normal tissues; similarly, the expression of GNG4 in rectal cancer was also significantly increased." (PMID 34691179, 2021). "Our group identified a 4-gene profile (C-MYC, GNG4, POLA, and RRM1) associated with response to preoperative chemoradiotherapy in rectal cancer patients." (PMID 26504848, 2015). "Seven hub genes, including SAA1, AGT, GNG4, GAL, CXCL1, CXCL2, and CXCL3, were upregulated in rectal cancer tissues." (PMID 34269159, 2021). "Besides CXCL1, CXCL2, and CXCL3, we mined seven other hub genes related to rectal cancer, including SAA1, AGT, GNG4, SST, SSTR2, GAL, and CXCL12." (PMID 34269159, 2021). "Colon cancer patients with high GNG4 expression had poor prognosis; however, the expression of GNG4 has no obvious relationship with prognosis in rectal cancer, which may be a result of fewer data points." (PMID 34691179, 2021).
colon cancer (5 papers, 2019 to 2025). "Herein, a comprehensive analysis using public databases of colon cancer (CC) was conducted, in which GNG4 was identified as an immunotherapy marker associated with prognosis." (PMID 37448185, 2023). "In previous studies, the tumor suppressor role of GNG4 has been mentioned in the core interaction network of colon cancer and it has been introduced as an important prognostic factor." (PMID 39552710, 2024). "According to the Kaplan–Meier plot with median expression of GNG4, the OS rate of colon cancer patients with high expression of GNG4 was lower than that of patients with low expression of GNG4 (P=0.027)." (PMID 34691179, 2021). "The expression of GNG4 was negatively related to overall survival (OS) of patients with colon cancer." (PMID 34691179, 2021). "MTT assay results showed that silencing of the GNG4 gene inhibited the proliferation of colon cancer cells." (PMID 34691179, 2021). "In addition, we found that GNG4 expression was lower in poorly differentiated colon cancer tissues compared with moderately/well differentiated colon cancer tissues." (PMID 37448185, 2023). "The in vitro experiments presented that after downregulating the expression of GNG4, proliferation, migration, and invasion of SW-620 colon cancer cells were all significantly reduced, apoptosis was significantly increased, and the cell cycle was blocked in the S phase." (PMID 34691179, 2021). "In our study, we report that the expression of GNG4 is upregulated in colon cancer." (PMID 34691179, 2021). "The expression of GNG4 in colon cancer increased with the cancer stage." (PMID 34691179, 2021). "This suggests that inhibiting the expression of GNG4 could induce cell cycle arrest of colon cancer cells in the S phase." (PMID 34691179, 2021). "VAV3, ACSL6, GNG4, and KRT23 were significantly enriched in gene set defined as “downregulated genes discriminating between MSI and MSS colon cancers”." (PMID 31008109, 2019).
gallbladder cancer (4 papers, 2021 to 2024). "Recent studies suggest that GNG4 expression is elevated in a variety of tumours, including colorectal, colon, gastric, lung adenocarcinoma, and gallbladder cancers, and is associated with poor prognosis in patients with these cancer types." (PMID 36845726, 2023). "Many previous studies have shown that GNG4 may be a diagnostic marker for various cancers, and GNG4 is highly expressed in different types of cancers, including rectal, colon, stomach, lung adenocarcinoma, and gallbladder cancers." (PMID 36845726, 2023). "GNG4 was also explored as a downstream target of PSMC2 in gallbladder cancer (GBC)." (PMID 36299585, 2022).
lung carcinoma (4 papers, 2018 to 2024). "In addition to our findings on LMO1, we identified five genes (GNG4, NCAPG, SPC25, ASPM and KIF2C) that are expressed at higher levels in lung tumors relative to NATs and are significantly correlated with poor survival of lung cancer patients, suggesting possible oncogenic functions in lung cancer." (PMID 30038707, 2018).
cognitive decline (3 papers, 2020 to 2024). "Lastly, GNG4 has been implicated in cognitive decline during aging and is downregulated in aged 5xFAD mice compared to age-matched WT." (PMID 32770063, 2020).
gastric cancer (3 papers, 2022 to 2024). A primary or metastatic malignant neoplasm involving the stomach. "High levels of GNG4 in primary cancer tissues are associated with short overall survival and high possibility of liver metastasis of gastric cancer, suggesting an oncogenic effect of GNG4." (PMID 39104385, 2024). "High levels of GNG4 were reported in primary gastric cancer tissues as well as liver metastatic lesions, which were associated with short overall survival (OS) and the likelihood of liver recurrence." (PMID 36397165, 2022). "GNG4 is also used as a biomarker in gastric cancer, especially in liver metastasis of gastric cancer." (PMID 35456499, 2022). "GNG4 is significantly upregulated in primary gastric cancer and liver metastasis." (PMID 39104385, 2024).
lung adenocarcinoma (3 papers, 2022 to 2023). A carcinoma that arises from the lung and is characterized by the presence of malignant glandular epithelial cells. "Increased GNG4 expression is related to the poor prognosis and hypoxic microenvironment in lung adenocarcinoma." (PMID 36397165, 2022). "The hypoxic microenvironment of lung adenocarcinoma could promote the expression of GNG4, and GNG4 promoted the migration and proliferation of LUAD cells." (PMID 35184748, 2022).
osteosarcoma (3 papers, 2022 to 2024). A usually aggressive malignant bone-forming mesenchymal neoplasm, predominantly affecting adolescents and young adults. "Furthermore, GNG4 was a good diagnostic marker for osteosarcoma, with an area under the receiver operating characteristic curve (AUC) of more than 0.9." (PMID 36845726, 2023). "In both the integrated GEO dataset and the GTEx + TARGET dataset, the expression of GNG4 in osteosarcoma was significantly higher than that in normal samples." (PMID 36845726, 2023). "Functional in vitro experiments were performed to explore the function of GNG4 in osteosarcoma cells." (PMID 36845726, 2023). "In in vitro experiments, silencing of GNG4 inhibited the viability, proliferation and invasion of osteosarcoma cells." (PMID 36845726, 2023). "The expression level of GNG4 between normal and osteosarcoma was identified in GSE12865 and GSE14359." (PMID 36845726, 2023). "Through bioinformatics analysis and experimental verification, high expression of GNG4 in osteosarcoma was identified as an oncogene and reliable biomarker for poor prognosis." (PMID 36845726, 2023). "This study helps to elucidate the significant potential of GNG4 in carcinogenesis and molecular targeted therapy for osteosarcoma." (PMID 36845726, 2023). "The results of the GSEA enrichment analyses indicate that GNG4 was closely related to the cell cycle and proliferation pathways of osteosarcoma cells, which was confirmed by in vitro experiments." (PMID 36845726, 2023). "Patients with osteosarcoma were divided into high- and low-GNG4 groups." (PMID 36845726, 2023). "In vitro, we found that GNG4 was highly expressed in osteosarcoma cells." (PMID 36845726, 2023). "Functional analysis suggested that GNG4 may promote the occurrence of osteosarcoma by regulating ossification, B-cell activation, the cell cycle and the proportion of memory B cells." (PMID 36845726, 2023). "This study aimed to elucidate the biological role and prognostic value of GNG4 in osteosarcoma." (PMID 36845726, 2023). "Based on previous studies, we speculated that GNG4 might inhibit memory B cells, thus promoting the occurrence and development of osteosarcoma." (PMID 36845726, 2023). "Based on the osteosarcoma single-cell RNA sequencing (scRNA-seq) dataset GSE162454, differential expression of GNG4 among cell subsets was identified at the single-cell level." (PMID 36845726, 2023). "However, a role for GNG12 and GNG4 in the mechanism of osteosarcoma progression has not been reported, which also provides a new direction for osteosarcoma research." (PMID 36685868, 2022).
depression (2 papers, 2016 to 2025). "The decreased expressions of mRNAs in CUMS-induced depression mice include Slc6a11, Hap1, Gad1, Gad2, Gng4, Slc32a1, Doc2g, Slc32a1, Magel2, Prkcd, Ngfr, Dusp1, Th, Itih3, Cacna2d2, Arc, Mbp, Peg10, Fos, and so on." (PMID 27427907, 2016).
hepatocellular carcinoma (2 papers, 2021 to 2025). A malignant tumor that arises from hepatocytes. "Besides GLS, two additional genes incorporated into the prognostic model- GNA14 and GNG4-may also contribute to hepatocellular carcinoma biology." (PMID 41348762, 2025).
prostate carcinoma (2 papers, 2022 to 2026). A carcinoma that arises from epithelial cells of the prostate gland. "Here, we identified the G protein subunit GNG4 as a crucial regulator of prostate cancer development." (PMID 41605902, 2026). "Our findings identified GNG4 as a pivotal modulator of prostate cancer progression and proposed it as a promising therapeutic target to enhance the clinical response to enzalutamide." (PMID 41605902, 2026). "GNG4 expression was markedly elevated in advanced prostate cancer phenotypes and positively correlated with tumor survival, apoptosis, and migration." (PMID 41605902, 2026).
renal cell carcinoma (2 papers, 2016 to 2022). "GNG4 as a potential tumor suppressor has been previously shown in renal cell carcinoma." (PMID 27382437, 2016).